HMGB1 (high mobility group box 1)
Diseases named in the same sentence as HMGB1 in open-access papers (continued):
Sharing a sentence is not in itself a finding about the gene and the disease.
Obesity (76 papers, 2013 to 2026). Accumulation of substantial excess body fat. "HMGB1-driven inflammation impairs insulin signaling in adipocytes and is associated with an increased risk of obesity-related complications, including cardiovascular disease and certain cancers." (PMID 40362460, 2025). "Step-wise regression was used to determine the mechanism order beginning with obesity-associated modulation of the gut microbiome and its downstream effects on HMGB1 and viral neutralization." (PMID 38172612, 2024). "One plausible mechanism implicated in obesity-induced ASM remodeling involves the participation of HMGB1." (PMID 38562155, 2024). "Although HMGB1 is actively involved in chronic inflammation, such as that associated with adipose tissue in obesity, measuring HMGB1 expression in the blood is challenged by the difficulty of selecting a group of patients with a high probability of IA." (PMID 39451983, 2024). "One promising avenue for exploring the impact of obesity on epithelial airway remodeling is to investigate its potential association with high mobility group box protein 1 (HMGB1)." (PMID 38562155, 2024). "Lymphocytes, neutrophils, platelets, TGF-β1 and HMGB1 have all been implicated in both pathogenesis and obesity-driven cancer." (PMID 36012397, 2022). "Since HMGB1 is closely linked to obesity and obesity-induced inflammation, we monitored the weight changes of WT and HC-HMGB1−/− mice weekly." (PMID 33238880, 2020). "As such, HMGB1 is associated with low-grade inflammation diseases, such as obesity and type 2 diabetes." (PMID 27843198, 2016). "Our study implicates the clinical potential of targeting inflammasome and HMGB1 signalling axis for the prevention of the early onset of obesity‐associated vasculopathy." (PMID 26293846, 2015). "Toll-like receptors and inflammasomes are activated in obesity by damage-associated molecular pattern molecules (DAMPs), such as high-mobility group box 1 (HMGB1) and oxidized low-density lipoprotein (Ox-LDL), RBP4 or PAMPs, such as LPS." (PMID 26779183, 2015). "A recent study found that n-3 polyunsaturated Fas (PUFA) could alleviate the progression of obesity-associated OA through modulation of the HMGB1-RAGE/TLR4 signaling pathway." (PMID 39744183, 2024). "Our results suggest that differential usage of HMGB1 isoforms during pancreas development may affect adult risk of developing obesity and/or T2D." (PMID 37903777, 2023). "We believe that our finding is related to the chronic and systemic inflammatory state caused by obesity and may be related to the still-unknown role of HMGB1 in disease development." (PMID 29619146, 2018). "HMGB1 is a protein responsible for high levels of inflammation that is linked to obesity." (PMID 30158958, 2018). "There are no published studies demonstrating the expression of this protein in lungs in an experimental model of obesity, but some previous work has shown that obesity is associated with increased expression of HMGB1 and inflammatory cytokines in the adipose tissue." (PMID 29619146, 2018). "Whether decreased sRAGE level in obesity reflects mainly the pro-inflammatory status, particularly associated with high HMGB1 levels, remains to be confirmed." (PMID 28409494, 2017). "In particular, enhanced signaling of the high mobility group box 1 (HMGB1) protein was found to associate with this dysregulation, with its upregulated levels in plasma associated with significantly impaired viral neutralization that was exacerbated with obesity." (PMID 38172612, 2024). "In obesity, elevated extracellular HMGB1 establishes a self-perpetuating inflammatory cycle in adipose tissue, where ongoing receptor signaling maintains inflammatory pathway activation in both adipocytes and resident immune cells." (PMID 40362460, 2025). "This discovery fills critical knowledge gaps and positions HMGB1 signaling at the intersection of metabolism and inflammation in obesity." (PMID 40362460, 2025).
Obesity (continued). "Stepwise pathway analysis of our data highlighted the role of the HMGB1 pathway in regulating the microbiome-immune axis in obesity-related PASC." (PMID 38172612, 2024). "Altogether, our findings show that increased HMGB1 pathway signaling in obesity impairs adaptive immune response to SARS-CoV-2, contributing to the development of PASC with persistent chronic effects." (PMID 38172612, 2024). "In T2D, HMGB1 promotes obesity-induced adipose inflammation, insulin resistance, and islet dysfunction." (PMID 37903777, 2023). "A study conducted in China reported that increased plasma HMGB1 was associated with insulin resistance, whereas increased serum HMGB1 was linked to pro-inflammatory cytokines induced by T2DM and obesity." (PMID 37239204, 2023). "Collectively, GLC alleviates steatohepatitis induced by alcohol consumption and obesity through inhibition of the HMGB1-mediated inflammatory cascade." (PMID 36278177, 2022). "In obesity-induced inflammation, there is an apparent interplay between HMGB1, NRF2 and NF-κB signalling pathways." (PMID 35406022, 2022). "Concordant with our results, Mona’s recent study demonstrated that sitagliptin suppresses inflammation by decreasing HMGB1-mediated TLR4/NF-κB signalling in a rat obesity model." (PMID 35163991, 2022). "HMGB1 acts as an innate pro-inflammatory mediator in WAT of patients with obesity by binding to TLR4 and triggering an inflammatory response." (PMID 35406022, 2022). "The levels of interleukin‐6 (IL‐6) in AT is about 100 times higher than that in plasma, and high mobility group box 1 (HMGB1) secretion in AT of patients with obesity is twice as higher than in normal‐weight individuals." (PMID 33332766, 2021). "It has been shown that HMGB1 is an important player in inflammatory pathways and the elucidation of the influence of HMGB1 in obesity-related inflammation would be intriguing for further studies." (PMID 34867969, 2021). "Receptor for advanced glycation end products (RAGE), which is highly expressed in monocytes and macrophages and its ligand, high mobility group box 1 (HMGB1), are also found to be associated with development of obesity." (PMID 33511131, 2020). "When analyzing the impact of irisin on adipocyte–macrophage interaction and obesity-related inflammation, proinflammatory alarmin HMGB1 should also be taken into account, whose elevated level has been noted in obese individuals." (PMID 31438646, 2019). "Though the mechanism underlying HMGB1 release during metaflammation is still obscure, some studies demonstrate that PKR, activated in liver tissues upon obesity and HFD feeding, triggers inflammasome-dependent HMGB1 release." (PMID 31215394, 2019). "Elevated HMGB1 was observed in pregnant women with other pro-inflammatory conditions as obesity and pre-term labor." (PMID 29149067, 2017). "The functional association among HMGB1, RAGE, and TLRs augments the inflammation in the course of T2D including obesity-induced inflammation, insulin resistance, and islet inflammation." (PMID 28101517, 2016). "In this review we will focus on the pathophysiological connections between HMGB1 and obesity, insulin resistance, and islet dysfunction." (PMID 28101517, 2016). "Recently, a study among obese children showed that obesity was positively correlated with increased HMGB1 serum levels and was related to a number of proinflammatory cytokines, such as IL-6 and TNF-α." (PMID 28101517, 2016). "Though previous studies have reported the role of circulating CTRP-3 and HMGB-1 in T2DM and obesity, there is little information concerning the associations of circulating CTRP-3 and HMGB-1 with pre-DM." (PMID 27738641, 2016). "AlthoughHMGB1 is reportedly associated with obesity in adolescents, research has rarely provided direct evidence to further confirm the relationship between T2DM,obesity and HMGB1." (PMID 26317615, 2015). "Serum HMGB1 participated in the pathological process of obesity and T2DM via its proinflammatory effect." (PMID 26317615, 2015).
Obesity (continued). "Extracellular HMGB1 as a cytokine is highly correlated with parameters of obesity, IR and inflammation." (PMID 26317615, 2015). "Last but not least, our study is cross-sectional, so we cannot explain the causality between plasma HMGB1 levels and T2DM or obesity." (PMID 26317615, 2015). "In the current study, although BMI does not significantly impact the immune microenvironment of PTC, HMGB1 is downregulated in underweight individuals and individuals with obesity, and ARG2 is upregulated in the obesity condition, suggesting their involvement in cancer-related processes." (PMID 40943211, 2025). "Obesity-induced epithelial remodeling may involve various factors, including HMGB1, the role of leptin, CysLTs, ORMDL3, matrikines like PGP, and cytokines such as IL-4 and IFN-γ, which may contribute to epithelial alterations." (PMID 38562155, 2024). "We hypothesized the increase in HMGB1 levels observed in higher BMI groups exacerbated chronic inflammation present in obesity due to increased adiposity." (PMID 38172612, 2024). "Indeed, HMGB1 is known to initiate and exacerbate inflammation with increased serum levels reported in obesity." (PMID 35406022, 2022). "FFAs also increases the synthesis of high-mobility group box 1 (HMGB1) protein, which might explain the early onset of endothelial injury during obesity by FFAs." (PMID 34529222, 2022). "Therefore, the effect of specific characteristics such as smoking history, racial difference, and obesity on healthy subjects' of HMGB1 and/or Hsp70 concentration in regional airways should be evaluated further." (PMID 33746593, 2021). "In obesity conditions, HMGB1 released by necrotic adipocytes interacts with RAGE, inducing the secretion of proinflammatory cytokines, and recruits immune cells that in turn induce additional adipocyte death through the further release of proinflammatory cytokines and ROS production." (PMID 34204735, 2021). "Together, these findings suggest that the NLRP3 inflammasome, HMGB1, TLR4, and possibly some other mediators might serve as promising therapeutic targets to counter visfatin-mediated vascular injury associated to obesity." (PMID 33182523, 2020). "Moreover, several epidemiological investigations revealed that HMGB-1 (one of the TLR4 ligands) can serve as an important diagnostic marker for insulin resistance and obesity." (PMID 31507457, 2019). "Likewise, previous findings have shown that interactions between intracellular RAGE and its endogenous ligand HMGB1 in adipose tissue, are also crucial in activating chronic inflammation in subjects with obesity." (PMID 31231489, 2019). "Following CORM-A1 treatment, HMGB1 levels were reduced in dietary-induced obese mice in comparison to those found for the other groups suggesting an antiinflammatory effect induced by CORM-A1 on obesity." (PMID 30158958, 2018). "In addition, several studies indicate that HMGB-1 is related to insulin resistance, obesity, and T2DM." (PMID 27738641, 2016). "Obesity has been associated with activation of pro-inflammatory pathways in the brain, as a high fat diet up-regulated expression of toll like receptor 4 (TLR4), high-mobility group protein B1 (HMGB1), vascular endothelial growth factor (VEGF) and COX-2." (PMID 27655189, 2016). "HMGB1 induced by free fatty acids promotes the tight junction disruption and endothelial hyperpermeability, ultimately contributing to the endothelial dysfunction and injury during obesity." (PMID 27689324, 2016). "Remarkably, little is known about the distribution of HMGB1 in fat tissues and whether the level of soluble HMGB1 (in blood and fat tissues) is increased in response to obesity." (PMID 24073286, 2013). "Interventions targeting the HMGB1 pathway may potentiate adipose tissue metabolic activity and improve metabolic health, offering a promising therapeutic avenue for millions affected by obesity-related conditions." (PMID 40362460, 2025).
Obesity (continued). "Thus, acupuncture may affect the regulation of obesity by inhibiting the activation of TLR4 via HMGB1 and thus downregulating NF-κB/IL-6 pathway." (PMID 36105933, 2022). "Therefore, platelet and neutrophil activation and tumor infiltration, TGF-β1/Smad2/3 signaling and HMGB1/RAGE signaling all play substantial roles in the obesity-driven aggressiveness of cancer, with each being a potential target for the anticancer actions of metformin." (PMID 36012397, 2022). "Therefore, we speculated that HMGB1 may act as a mediator of inflammatory response in an early stage of steatohepatitis induced by alcohol consumption and obesity." (PMID 36278177, 2022). "Thus, it was hypothesized that the inflammation due to adipose tissue expansion in obesity could be exacerbated by Nucb2 knockdown and lead to upregulation of HMGB1." (PMID 35406022, 2022). "Moreover, HMGB1 may be involved in induction of the pro-inflammatory status in adipose tissue during obesity." (PMID 32973755, 2020). "Consequently, HMGB1 can disrupt inter-endothelial junctions and increase paracellular permeability of the endothelium via paracrine and autocrine signaling, resulting in early stage endothelial injury during metabolic disorders such as obesity." (PMID 33182523, 2020). "DAMP proteins HMGB1 and S100B were identified as potential targets for assessing pro-inflammatory signaling in hibernating ground squirrels because both are highly expressed in adipose tissues, and are upregulated in diet-induced obesity mice models and following high fat diets in mice." (PMID 29888131, 2018). "Together, these data strongly suggest that activation of endothelial inflammasomes due to increased free fatty acids produces HMGB1, which disrupts inter-endothelial junctions and increases paracellular permeability of endothelium contributing to early onset of endothelial injury during obesity." (PMID 27689324, 2016). "Hence, the HMGB1 protein modulated autophagy-related proteins and lipid-metabolism-related genes in adipocytes and could be a new target for treatment of obesity and related metabolic diseases." (PMID 27843198, 2016). "A possible shortcoming of our study was that the levels of sTLR4 or HMGB1 may be affected by many factors, such as infection, certain medicines, or even obesity; hence, large variations in serum levels of sTLR4 and HMGB1 were found between NSCLC patients even within the same stages." (PMID 27223258, 2016). "Therefore, the clinical significance of HMGB1 deserves to be explored in obesity and T2DM patients." (PMID 26317615, 2015). "The development of obesity-induced ASM remodeling is an intricate process influenced by factors like neutrophils, neutrophil elastase, CD4+ T cells, HMGB1 protein, TGF-β1, leukotrienes, and their derivatives." (PMID 38562155, 2024). "The functional interplay between HMGB-1, RAGE, and TLRs exacerbates inflammation in T2D, including inflammation induced by obesity, insulin resistance, and islet inflammation." (PMID 39271468, 2024). "The knockdown of integrin α5β1 attenuated FFA-induced caspase-1 cleavage and excessive lipid accumulation, reducing HMGB1 and GSDMD-NT protein levels, indicating its participation in pro-inflammatory pyroptosis during obesity." (PMID 36145246, 2022). "Meanwhile, other important mediators and signaling pathways have been noted in the literature, including the crosstalk between HMGB1, Hsp72 and RAGE/ERK1/2 signaling, which is a metabolic pathway common to obesity and bronchial asthma." (PMID 34118928, 2021). "HMGB1 released by necrotic adipocytes interacts with RAGE, inducing pro-inflammatory cytokines and ROS;S100A4, S100A8/A9, and S100B induce inflammation, interacting with RAGE;AGE accumulation in adipose tissue may contribute to obesity-associated insulin resistance." (PMID 34204735, 2021).
Obesity (continued). "RT-qPCR results showed that, compared with the control group, mRNA expression levels of VEGFA, VEGFR-2, CD31, and SIRT1 were significantly decreased in the obesity group (P < 0.001), while the expression levels of GLUT1, HIF-1α, TNF-α, IL-6, HMGB1, and TLR4 were significantly upregulated (P < 0.01)." (PMID 41505418, 2026). "Immune cell activation in obesity is primarily triggered by DAMPs, such as free fatty acids, low-density lipoprotein cholesterol (LDL-c), uric acid, high-mobility group box 1 (HMGB1) protein, mitochondrial deoxyribonucleic acid (DNA), and extracellular adenosine triphosphate (ATP)." (PMID 41155165, 2025). "Specifically, IPA identified the high mobility group box 1 (HMGB1) protein as a top pathway implicated by the data independent of body mass index (BMI), although HMGB1 response was perturbed in obesity." (PMID 38172612, 2024). "Although previous studies describe independent links between obesity, inflammation, the gut microbiome, and HMGB1, none show that these systems together influence PASC." (PMID 38172612, 2024). "There is increasing evidence linking HMGB1 with T2DM and obesity." (PMID 37239204, 2023). "Irrespective of TACE, the average HMGB1 in hepatitis and obesity patients was higher than that in normal individuals, which was not upregulated after TACE." (PMID 34583662, 2021). "Moreover, high mobility group box 1 (HMGB1), a pro-inflammatory adipocytokine involved in WAT inflammation and insulin resistance in patients with obesity was secreted by adipocytes in response to JNK signaling." (PMID 32872540, 2020). "Upon obesity or HFD feeding, many exogenous and endogenous stimuli, such as bacterial endotoxin, cytokines, cell stress and damage, provoke the expression and secretion of HMGB1." (PMID 31215394, 2019). "The use of anti-HMGB1 neutralizing antibody effectively reduce HFD-induced weight gain and liver inflammation in mice, suggesting that TLR4 is likely a key therapeutic target for dyslipidemia and obesity." (PMID 31507457, 2019). "In summary, we detected HMGB1 serum levels in patients with T2DM and obesity or both." (PMID 26317615, 2015). "Mature human adipocytes undergo senescence under obesity and hyperinsulinemia stimulation, exhibiting premature aging transcriptomic and secretory characteristics, including upregulation of CDKN2A, CDKN1A, and CCND1 gene expression, and downregulation of HMGB1 and HMGB2 gene expression." (PMID 39963130, 2025). "Meanwhile, miR-216a-5p may be combined with HMGB1 protein and sRAGE (soluble RAGE) to construct a multivariate predictive model to individualize the management for patients with simple DN or complicated with cardiovascular diseases or obesity in clinical scenarios." (PMID 41163685, 2025). "The IL6/ADPN/HMGB1 axis was differentially expressed in human subepicardial tissue and blood samples, and was an independent factor in patients with CAD, which may partly explain the obesity paradox in patients that are overweight or obese, particularly among those who develop symptomatic CAD." (PMID 38601146, 2024). "The interaction between HMGB1 and RAGE has been previously shown to result in the secretion of inflammatory cytokines, suggesting that the increased expression of HMGB1 in patients with GDM may contribute to the chronic inflammatory state, which is relevant to obesity and insulin resistance." (PMID 37691930, 2023). "However, another RAGE ligand – pro-inflammatory cytokine high mobility group protein box-1 (HMGB1), displaying 10-fold higher binding affinity to RAGE in comparison with AGEs, circulates in concentrations similar to those of sRAGE, and has been shown to be increased in obesity." (PMID 28409494, 2017). "Upregulated HMGB1 elevated the prognosis after TACE, but obesity and HBV infection resulted in the negative effect by inhibiting HMGB1 expression." (PMID 34583662, 2021).
Obesity (continued). "There is currently no published report regarding HMGB1 expression and functions in fat cells and possible links to LGI in obesity." (PMID 24073286, 2013).